FKBP8 (FKBP prolyl isomerase 8)
Description:
Constitutively inactive PPiase, which becomes active when bound to calmodulin and calcium. Seems to act as a chaperone for BCL2, targets it to the mitochondria and modulates its phosphorylation state. The BCL2/FKBP8/calmodulin/calcium complex probably interferes with the binding of BCL2 to its targets. The active form of FKBP8 may therefore play a role in the regulation of apoptosis. Involved in the inhibition of viral infection by influenza A viruses (IAV).
Synonyms: FKBP38; FKBPr38
Tractability: Small molecule: it belongs to a druggable protein family. Antibody: UniProt predicts a signal peptide or a membrane-spanning region. PROTAC: UniProt records ubiquitination sites on it; ubiquitination databases record sites on it; its protein half-life has been measured.
Target class: Isomerase; Enzyme
Gene: Protein-coding gene on chromosome 19 (18,531,751 to 18,544,264, reverse strand). Ensembl gene ENSG00000105701.
Subcellular location: Mitochondrion; Mitochondrion membrane; Mitochondrion membrane (Isoform 1); Mitochondrion membrane (Isoform 3)
Subcellular location (Human Protein Atlas): Mitochondria; Cytosol; Endoplasmic reticulum
Pathways (Reactome):
Metabolism of proteins: Ub-specific processing proteases
Gene Ontology:
Molecular function: calmodulin binding; disordered domain specific binding; identical protein binding; protein binding; protein folding chaperone; peptidyl-prolyl cis-trans isomerase activity
Biological process: negative regulation of protein phosphorylation; protein folding; protein localization to mitochondrion; regulation of mitophagy; intracellular signal transduction; negative regulation of apoptotic process; signal transduction
Cellular component: membrane; mitochondrial membrane; mitochondrion; protein-containing complex; cytosol; endomembrane system; mitochondrial envelope; endoplasmic reticulum membrane
Genetic constraint (gnomAD): Loss-of-function variants: 5 observed, 39.5 expected, observed/expected ratio (o/e) 0.13, 90% interval 0.065 to 0.27. The upper end of that interval is the gene's LOEUF score, 0.27, which puts it in group 1 of 6, group 1 being the genes least tolerant of losing a copy. Missense variants: 397 observed, 563.51 expected, observed/expected ratio (o/e) 0.7, 90% interval 0.65 to 0.77. Synonymous variants: 279 observed, 258.97 expected, observed/expected ratio (o/e) 1.08, 90% interval 0.98 to 1.19.
Homologues: Orthologues: chimpanzee FKBP8 (99% identical), macaque FKBP8 (99% identical), dog FKBP8 (97% identical), guinea pig FKBP8 (93% identical), rat Fkbp8 (91% identical), mouse Fkbp8 (91% identical), pig FKBP8 (90% identical), tropical clawed frog fkbp8 (57% identical), zebrafish fkbp8 (55% identical), Caenorhabditis elegans fkb-5 (9% identical), Caenorhabditis elegans fkb-4 (8% identical), Drosophila melanogaster Fkbp39 (7% identical). Paralogues in human: FKBP4 (19% identical), FKBP15 (18% identical), FKBP6 (18% identical), FKBPL (17% identical), FKBP5 (17% identical), FKBP10 (12% identical), FKBP9 (12% identical), FKBP11 (9% identical), TTC9 (9% identical), FKBP7 (9% identical), TTC9B (9% identical), FKBP14 (8% identical), and 6 more.
Diseases named in the same sentence as FKBP8 in open-access papers:
FKBP8 is named in the same sentence as 32 diseases in open-access papers, as found by Europe PMC text mining. Sharing a sentence is not in itself a finding about the gene and the disease. The quoted sentences say what the papers report.
glioblastoma (3 papers, 2018 to 2023). The most malignant astrocytic tumor (WHO grade IV). "While in some cases the pro-tumorigenic function of SPP could be delineated to processing of individual substrates like HO-1 or FKBP8, the molecular mechanism underlying the pro-tumorigenic function of SPP in EGFRvIII glioblastoma is not as well understood." (PMID 32052089, 2020).
hyperlipidemia (3 papers, 2023 to 2024). "FKBP8/38 agonists can reduce fat-induced hyperlipidemia, with hyperlipidemia being a key feature of dysferlinopathy in LGMD2B/LGMDR2." (PMID 36902136, 2023).
lung carcinoma (3 papers, 2020 to 2025). "While the substrates responsible for the pro-tumorigenic effect of SPP in GBM currently remain elusive, a crucial involvement of the newly identified SPP substrate FKBP8 was demonstrated in breast and lung cancer cell lines." (PMID 32052089, 2020). "A SILAC-based proteomic analysis of a lung cancer cell line treated with siRNA against SPP identified FKBP8 as a novel SPP substrate." (PMID 32052089, 2020).
lentivirus infection (2 papers, 2024 to 2025). Virus diseases caused by the Lentivirus genus. "To estimate the contribution of FKBP8 receptor to oxidative stress-induced mitophagy, we depleted endogenous FKBP8 in our stable cell lines expressing mt-mKeima using lentivirus infection." (PMID 39026868, 2024).
Sepsis (2 papers, 2021 to 2024). Sepsis is defined as life-threatening organ dysfunction caused by a dysregulated host response to infection. "Therefore, we speculate that FKBP8 can serve as an innovative target for mitochondrial therapy, especially in terms of immune therapy, thus providing a new avenue for the clinical treatment of sepsis." (PMID 38755528, 2024). "In this study, we identified for the first time that four mitochondrial genes (FIS1, FKBP8, GUK1, GLRX5) can significantly impact the prognosis of sepsis patients, with high sensitivity and specificity for sepsis." (PMID 38755528, 2024). "We compared the gene expression levels of both groups and found that FIS1, FKBP8, GLRX5, and GUK1 were underexpressed in the sepsis group but overexpressed in the SIRS group." (PMID 38755528, 2024). "Mitochondria-related genes (FIS1, FKBP8, GLRX5, GUK1) were underexpressed in the sepsis group, negatively correlated with survival, and mainly distributed in immune cells." (PMID 38755528, 2024). "In 26 upregulated OCRGs in AIs, the upregulation of two regulators, SERPINA1 and AZU1, was shared among acute respiratory distress syndrome (ARDS), sepsis, and trauma; upregulation of CD24 and FKBP8 was shared among ARDS and trauma; and upregulation of GRN was shared between sepsis and trauma." (PMID 34368262, 2021).
spina bifida (2 papers, 2021 to 2023). A congenital neural tube defect in which vertebrae are not fully formed. "Studies based on a knockout mouse model showed that Fkbp8 (FK506 binding protein-8) mutation leads to the development of spina bifida." (PMID 37284286, 2023). "Mutations in a different TPR-containing cochaperone, FKBP38 (encoded by FKBP8), have been identified as risk factors for spina bifida, a neural tube defect." (PMID 34957217, 2021).
tauopathies (2 papers, 2024 to 2025). "Specifically, our results indicate that FKBP8 translocation to the ER appears to protect it from degradation -a protective mechanism that may be suppressed in tauopathies." (PMID 39026868, 2024).
coronary atherosclerosis (1 paper, 2024). Atherosclerosis of the coronary vasculature. "A previous study has found that FKBP8 is significantly correlated with the extent of coronary atherosclerosis." (PMID 38598492, 2024).
cystic fibrosis (1 paper, 2021). Autosomal recessive disorder caused by pathogenic variants in the CFTR gene (cystic fibrosis transmembrane conductance regulator), which encodes a chloride and bicarbonate channel expressed in epithelial cells, and follow the diagnosis criteria. "In contrast, despite its well established role in ER biogenesis, FKBP8 does not appear to contribute to trafficking and membrane stabilization of WT and mutant Cl− channels implicated in cystic fibrosis." (PMID 34070744, 2021).
influenza infection (1 paper, 2016). "DBALIS found that overexpression of TRIM32, STUB1 and FKBP8 reduced influenza infection activity from two to four fold, indicating their role in viral restriction." (PMID 27375580, 2016).
liver cancer (1 paper, 2022). An epithelial or non-epithelial malignant neoplasm that arises from the liver. "In this study, we find that FKBP8 is overexpressed in liver cancer and correlates with poor survival in HCC patients." (PMID 35970393, 2022). "Functionally, we reveal that FKBP8 demethylation by KDM1A is critical for liver cancer cell growth in vitro and in vivo." (PMID 35970393, 2022). "Meanwhile, TCGA dataset suggested that higher FKBP8 level correlates with poorer survival in liver cancer patients." (PMID 35970393, 2022).
medulloblastoma (1 paper, 2021). A malignant, invasive embryonal neoplasm arising from the cerebellum. "The seven circRNAs, FKBP8, SMARCA5, GLIS1, BACH1, ZKSCAN1, CDYL, and OGDH, with a reduced expression in medulloblastoma versus cerebellum, while their corresponding linear mRNAs do not follow this change of expression pattern, were selected for further analysis." (PMID 34680287, 2021).
viral infection (1 paper, 2017). "Consistently, PKP2, FKBP8, TRIM41 and ZMPSTE24 inhibited viral infection of NY/2009 and WSN/33." (PMID 28169297, 2017).
cancer (8 papers, 2014 to 2023). A tumor composed of atypical neoplastic, often pleomorphic cells that invade other tissues. "Fkbp8 has further functions in regulation of cell cycle progression and cancer by triggering the degradation of Prl-3 via the 26S proteasome." (PMID 24637697, 2014). "However, the current research on FKBP8 is limited to cancer and neurological diseases, and the role of FKBP8 in cardiovascular diseases still needs to be further explored." (PMID 37039609, 2023). "FKBP8 promotes resistance to apoptosis in cancers of epithelial origin." (PMID 35970393, 2022). "Genes and AS events enrolled in the comprehensive prognostic signature included RHOT1 (ES), SH3KBP1 (AP), AGTRAP (AA), PACS2 (AP), RBPMS (AT), B3GNTL1 (AP), MOBP (AT), NPHP3 (ES), ABCC5 (RI), FKTN (ES) and FKBP8 (AA), many of which are known to play important roles in cancer biology." (PMID 32467664, 2020). "Interestingly, AVPI1, FKBP8, and ALDH2, which were most negatively correlated with NUP205 in LGG, were all reported to be tumor suppressor genes in cancer." (PMID 37284202, 2023).
tumor (8 papers, 2014 to 2025). "FKBP8 is an endogenous inhibitor of mTOR, its degradation promotes tumor progression." (PMID 32467664, 2020). "Besides that BCL2, FKBP8, and KDM1A were increased in tumor compared with normal tissues, we also observed significant correlation between KDM1A and BCL2 protein level." (PMID 35970393, 2022). "It has been shown that the upregulated hub MMRG genes BCL2, MAVS, FKBP8, NBR1, and SLC25A6 and their products can participate in regulating drug resistance of tumour cells and the antitumour immune response and may be associated with the activation of inflammatory signalling pathways." (PMID 41463291, 2025).
cardiovascular diseases (2 papers, 2023 to 2025). "FKBP8 is implicated in cardiovascular diseases, and studies in mammals suggest developmental abnormalities." (PMID 39940747, 2025).
infection (1 paper, 2020). The state of being infected such as from the introduction of a foreign agent such as serum, vaccine, antigenic substance or organism. "This showed that levels of FKBP8 from the culture supernatant were not substantially different between the infection and the clearance stage." (PMID 32298370, 2020).
metabolic disease (1 paper, 2023). A congenital disorder (due to inherited enzyme abnormality) or acquired (due to failure of a metabolically important organ) disorder resulting from an abnormal metabolic process. "On this basis, a more in‐depth investigation of the specific mechanisms of FKBP8 and BCL2L13‐related mitophagy pathways in MS‐related metabolic diseases such as IR and T2DM can help to understand the role of mitophagy in MS more comprehensively and thorough." (PMID 37039609, 2023).
FKBP8 also shares sentences with these, for which no sentence is quoted: breast carcinoma (2 papers); hepatocellular carcinoma (2); iron deficiency (2); acute respiratory distress syndrome (1); colitis (1); COVID-19 (1); dysferlinopathy (1); Hyperglycemia (1); Insulin resistance (1); metastatic cancers (1); multiple sclerosis (1); myotonia congenita (1); neurological diseases (1); prostate adenocarcinoma (1).